EGR1 (early growth response 1)
Diseases named in the same sentence as EGR1 in open-access papers (continued):
Sharing a sentence is not in itself a finding about the gene and the disease.
cancer (continued). "Together, these data indicate that the NOX2/Egr-1/Fyn pathway is also pertinent to other TKI-resistant cancer types." (PMID 26136341, 2015). "Taken together, cancer-derived EVs induce Egr-1 activation by increasing its expression and nuclear translocation in endothelial cells." (PMID 25502753, 2014). "Taken together, these data indicate that Egr-1 activation in endothelial cells is a crucial mechanism involved in cancer-derived EV-induced angiogenesis." (PMID 25502753, 2014). "The reduced level of EGR1 before knockdown of BSP corresponds to the observation that cancer cells often become resistant to apoptosis." (PMID 24980816, 2014). "We find that the three genes that contribute the most to the formation of long feedback loops in the cancer cell line (EGR1, FOSL1, and JUNB) are all involved in the formation of the longest incomplete feedback loops observed in the non-cancer cell line." (PMID 25182846, 2014). "The metalloproteinases MMP-2 and MMP-9 are involved in the regulation of cancer cell migration and metastasis, while the transcription factor EGR-1 participates in the regulation of cell proliferation, migration and apoptosis." (PMID 25260978, 2014). "Egr-1 is, therefore, participating in the progression of a variety of diseases such as atherosclerosis or cancer." (PMID 24925061, 2014). "In the present study, we provide evidence that Egr-1 activation in endothelial cells is a key mechanism involved in the angiogenic activities of cancer-derived EVs." (PMID 25502753, 2014). "In this report, we provide evidence that Egr-1 activation in endothelial cells should be a key mechanism involved in the angiogenic activity of cancer-derived EVs." (PMID 25502753, 2014). "In summary, our study has revealed that Egr-1 activation in endothelial cells is a crucial mechanism of cancer-derived EV-induced angiogenesis." (PMID 25502753, 2014). "In fact, FOS, FOSB and EGR1 are proteins that have been reported to be down-regulated in several human carcinomas suggesting a critical role of these proteins in cancer progression." (PMID 24865347, 2014). "Loss of Egr-1 expression has been associated with invasion and anti-apoptotic events, whereas overexpression of Egr-1 suppressed the tumorigenicity and metastatic potential in several cancer cells including lung." (PMID 24925061, 2014). "Overexpressing Egr-1 in these cancer cell lines activated the basal transcriptional activity of EGF-R promoter by direct DNA-binding, which enhanced EGF-R expression." (PMID 23763269, 2013). "EGR-1 is a master regulator that plays an important role in a variety of cellular processes in cancer cells." (PMID 23658821, 2013). "Treatment of human carcinoma KB cells with Egr1 siRNA led to a decrease in IL6 and IL8 promoter activation, and Egr1 was found to bind to the promoters of both interleukins." (PMID 23342084, 2013). "It contains the protocadherin gene cluster, PCDHA, B and G and genes involved in cancer such as EGR1, CTNN1A, JMJD1B, and CXXC5." (PMID 23293768, 2012). "By immunohistochemical and Western immunoblotting analysis it was shown, that Egr-1 expression is significantly increased in patients with cachexia and cancer." (PMID 22721276, 2012). "AP-1, STAT3, and EGR1 are considered important transcription factors that are involved in regulating gene expression in human cancers, including HNSCCs." (PMID 17498291, 2007). "Thus, our studies uncover ESSENCE as an important cancer biomarker upregulated by the EGFR/MAPK/EGR1 pathway and also provide insight into CRC diagnosis and treatment." (PMID 40190348, 2025). "Notably, MP7 was associated with stress meta program (MP5) in pan‐cancer studies, sharing 14 common genes, including ATF3, EGR1, FOSB, GADD45B and NR4A1." (PMID 40292733, 2025).
cancer (continued). "EGR1 (Early Growth Response 1) is a transcription factor that regulates the expression of various genes involved in cell growth, differentiation, and survival, playing a significant role in cancer development and progression." (PMID 41154654, 2025). "The Cancer Genome Atlas (TCGA) database was utilized to examine the expression of EGR1 in ccRCC." (PMID 39866235, 2025). "Furthermore, the localization of ATF5 in the nuclei suppressed the transcription of EGR1, a protein that prevents the proliferation of cancer cells." (PMID 40124511, 2025). "Previous studies showed that EGR1 plays bidirectional roles in cancer progression." (PMID 40124511, 2025). "EGR1 is involved in growth and differentiation and plays a dual role in cancer biology." (PMID 40565055, 2025). "For example, a recent study showed that EGR1 may promote cancer metastasis via facilitating angiogenesis." (PMID 39741182, 2025). "Otherwise, if increased angiogenesis appears as dysregulation, as a likely possibility, regardless of beneficial effects, there is a considerable probability that increased angiogenesis precedes the complications and impedes uncontrolled VEGF, the egr-1 gene, carcinoma, and the NO-system." (PMID 40573323, 2025). "However, the specific role of EGR1 in cancer metabolism remains uncertain, and previous investigations lacked the genes expression profile detection for mechanistic analysis after EGR1 gene perturbations." (PMID 38287371, 2024). "Besides, various kinds of cancer cells secrete extracellular vesicles to ameliorate the migration of vascular endothelial cells by launching the expression of Egr1." (PMID 37989866, 2024). "Furthermore, the efficacy of EGR1 gene therapy was validated using in vivo mouse HCC models and in vitro human hepatoma organoid models, thereby providing additional substantiation for the anti-cancer role of EGR1 in HCC." (PMID 38287371, 2024). "EGR1 is considered to have a greater tendency to function as an anti-cancer factor." (PMID 39062453, 2024). "Moreover, EGR1 is aberrantly expressed in different types of cancers and is involved in their development." (PMID 38408959, 2024). "Moreover, we found that Egr1 can effectively inhibit the occurrence of cancer by mediating Apelin and AGE–RAGE." (PMID 38647922, 2024). "As a substrate of CRL1, EGR1 can be stabilized in cancer cells following MLN4924 treatment." (PMID 39062453, 2024). "Notably, one of these clusters exhibited a significant expression of cancer‐promoting genes, encompassing Cdkn1a, Plaur, Ptgs2, Cox17, Lilrb4q, G0s2, Egr1, and Cxcl2." (PMID 39113226, 2024). "EGR1 overexpressed in several cancers types, consistent with its known oncogenic role." (PMID 39501082, 2024). "We then explored whether the promotion of EGR1-mediated angiogenesis by nPD-L1 is context-dependent (a special case in UM) or a wide-ranged function in cancers." (PMID 36977660, 2023). "This study aimed to investigate whether EGR1 can regulate VM in aggressive cancer cells and to identify EGR1-target genes and signaling pathways." (PMID 37762678, 2023). "Therefore, to investigate the involvement of EGR1 in the VM formation of cancer cells, we examined EGR1 expression during VM formation." (PMID 37762678, 2023). "RRAD further inhibited transcription of EGR1 in cancer genesis." (PMID 36979412, 2023). "EGR1 could play an important role in tumorigenesis and cancer progression by transcriptional activation its targets." (PMID 36805440, 2023). "At present, there are many potential applications of the Egr-1 gene in cancer therapy." (PMID 35806184, 2022). "EGR1 activates apoptosis in several cancers via pro-apoptotic gene activation." (PMID 35418059, 2022). "However, after adjusting for the pathological stage, patients with EGR-1 expression > 68th percentile had lower risks of cancer-related death." (PMID 36233659, 2022). "Recent reports have shown the involvement of EGR1 in the initiation and succession of cancer." (PMID 35885958, 2022).
cancer (continued). "This module included a number of immediate early and growth factor response genes and overlapped with modules previously identified for SDF1 responses in PBs (genes such as CD69 and NR4A2) and growth factor responses in cancer (genes such as EGR1/3, FOS, FOSB, and IER2)." (PMID 36130130, 2022). "In addition, gene silencing with scrambled siRNA or siRNA against EGR-1 was employed to inspect the role of EGR-1 in cancer cell migration, invasion, and cell viability in response to chemotherapeutic agents in ESCC cells." (PMID 36233659, 2022). "The stemcell niche environment is rich in other growth factors, such as fibroblast growth factor-2 (FGF-2) and epidermal growth factor (EGF), that induce Id expression through the ERK–MEK pathway in cancer cells by direct binding of early growth responsive protein 1 (Egr-1) to the Id promoter." (PMID 34302526, 2022). "Early growth response-1 (EGR1) is a multi-domain protein and a transcription factor that participates in multiple key physiological processes including development, metabolism and proliferation, and in cancer development." (PMID 34409922, 2021). "The presence of multiple binding sites for EGR1 emphasizes the biological importance of this interaction and may represent a robust pathway to control Nm23-H1 expression and cancer metastasis." (PMID 33436746, 2021). "The EGR1 reduction was also observed in clinical cancer tissues." (PMID 34497759, 2021). "Studies suggested that Egr1 was a cancer suppressor gene and transcriptional regulator." (PMID 33479397, 2021). "As a transcription factor, EGR1 has a crucial role in human cancers." (PMID 34497759, 2021). "Indeed, analyses from the UALCAN database revealed that the expressions of SP1, ELK1, and EGR1 were remarkably aberrant in many TCGA cancer types." (PMID 35003212, 2021). "In HNC, elevated GDF15 promotes cancer progression via transcriptional regulation by EGR1." (PMID 34681812, 2021). "EGR1 was confirmed as a cancer suppressor by targeting CD24A in HCC." (PMID 32849835, 2020). "EGR1 is induced by treatment with anti-HER2 targeted therapies, including trastuzumab, and its expression is associated with favorable outcome in HER2 positive cancer models." (PMID 32085669, 2020). "One attractive hypothesis is that the tendon matrix environement regulated by EGR1 is protective against cancer." (PMID 32121305, 2020). "EGR1 can reduce apoptosis of cancer cells and promote their migration and angiogenesis." (PMID 32784711, 2020). "Single-Cell Regulatory Network Inference and Clustering (SCENIC) analyses showed that KLF6 was most significantly upregulated, while EGR1 was most significantly downregulated in GGN-ADC-derived cancer cells when compared with SADC cancer cells based on the area under the curve (AUC) scores." (PMID 33083004, 2020). "In addition, previous studies showed that miR-192 was involved in progression of human cancers through regulating expressions of target genes, such as Egr1 and TCF7." (PMID 32013999, 2020). "Nevertheless, the interaction and clinical significance of Oct4 and Egr1 remain unclear in cancer cells." (PMID 31399076, 2019). "However, as shown in this study, EGF was found to significantly upregulate EGR1 expression and increase cancer cell invasion." (PMID 30845713, 2019). "As a member of the early gene family, Egr-1 has an important role in drug resistance in cancer cells and could regulate the expression of CTSL." (PMID 31370861, 2019). "The roles of EGR1 in cancer development are ambiguous since EGR1 may act as either oncogene or tumor suppressor gene in different cancer types." (PMID 31501409, 2019).
cancer (continued). "Recently, a few studies have elucidated that Egr1 may be involved in cancer progression or act against cell apoptosis." (PMID 31399076, 2019). "Recent studies suggest that Egr-1 is also involved in drug resistance in cancer cells." (PMID 31370861, 2019). "Among these genes, EGR1, Fos Proto-Oncogene (FOS), FosB Proto-Oncogene (FOSB), Jun Proto-Oncogene (JUN), Dual Specificity Phosphatase 6 (DUSP6) and CTGF have been previously implicated in cancer metastasis." (PMID 30792382, 2019). "Therefore, we aimed to evaluate how EGF increases cancer cell invasion during conditions of EGR1 upregulation." (PMID 30845713, 2019). "This suggests that both Egr-1 and miR-20b are potent targets for cancer therapy." (PMID 30400241, 2018). "The health outcome associated with arsenic exposure in utero and through childhood was increased cancer risk, where hypomethylation of inflammatory genes (COX2, EGR1, and SOC3) positively correlated with levels of 8-nitroguanine, increased DNA damage and reduce DNA repair capacity." (PMID 30835380, 2018). "EGR1 has been previously indicated in the induction of apoptosis in a variety of cancers." (PMID 29719592, 2018). "Alternatively, Egr-1 may also act to inhibit cancer progression by targeting, for instance, miR-203a, which functions as an anti-oncogene." (PMID 30400241, 2018). "Increasing evidence suggests that Egr-1 stimulation may act as a master alteration in many pathological processes, including cardiovascular diseases and cancers." (PMID 30400241, 2018). "However, two opposing actions of EGR1, tumor suppressor and oncogene, have been described in different cancer cells." (PMID 29246166, 2017). "The global changes observed at the two-cells stage could account for the enrichment of egr1 and the cancer pathway at this stage." (PMID 28531178, 2017). "Together, our findings suggest that the NOX2/Egr-1/Fyn signaling axis may represent a novel target in TKI-resistant cancers, particularly in a population of treatment-refractory stem cells." (PMID 26136341, 2015). "GROβ contributed dramatically to the elevated transcription of EGR-1 in cultured cancer cells." (PMID 25944970, 2015). "Type 1-specific genes would be regulated in an all-or-none manner by either of these two feedforward loops that associate with the robust miR-199a/Brm/EGR1 axis that dictates cancer cell lines to either of the steady states, [miR-199(−)/Brm(+)/EGR1(−)] and [miR-199a(+)/Brm(−)/EGR(+)]." (PMID 25673149, 2015). "Together, these data suggest that the NOX2/Egr-1/Fyn pathway may also have potential for the eradication of cancer stem cells across cancer types." (PMID 26136341, 2015). "Egr-1 itself has varying roles in cancer depending on the cellular context." (PMID 26136341, 2015). "Several candidate gene products (UCHL1, SNAT1, and EGR1) were selected to investigate whether PRR11 influences their expression in HC cancer cells." (PMID 25971332, 2015). "Finally, EGR1 has been shown to induce apoptosis in cancer cells when up-regulated by NSAIDs, thus the role of EGR1 is controversial." (PMID 26498686, 2015). "EGR1 translation is inhibited by miR-183 in different cancer cells, including HCT116." (PMID 26343742, 2015). "Thus, to determine if the NOX2/Egr-1/Fyn pathway was active in another kinase-driven cancer type, we first mined data from two independent data sets." (PMID 26136341, 2015). "Together, these data suggest that the NOX2/Egr-1/Fyn pathway may be a novel therapeutic target for the eradication of the more treatment resistant cancer stem cell populations." (PMID 26136341, 2015). "Together, these data suggest that the NOX2/Egr-1/Fyn pathway is present in multiple cancer types where it may promote a TKI-resistance phenotype." (PMID 26136341, 2015). "However, further studies on Egr-1 knockout mice should be carried out to understand the exact role of endothelial Egr-1 during cancer EV-induced neovascularization." (PMID 25502753, 2014).
cancer (continued). "As a consequence, EGR1 is often downregulated or lost in human cancer tissues and cell lines." (PMID 24787739, 2014). "Thus, rapid and transient regulation of Egr-1 expression and activation after stimulation with cancer-derived EVs should contribute to EV-induced endothelial cell activation and in vitro angiogenesis." (PMID 25502753, 2014). "And EGR1 was more up-regulated in pericancerous liver but less up-regulated in cancer liver." (PMID 24564407, 2014). "Our results suggest that Egr-1 activation in endothelial cells may be a key mechanism involved in the angiogenic activity of cancer-derived EVs." (PMID 25502753, 2014). "Furthermore, lipid raft-mediated endocytosis inhibitor effectively blocked endothelial Egr-1 activation and migration induced by cancer-derived EVs." (PMID 25502753, 2014). "Thus, our findings suggest that Egr-1 is a crucial proangiogenic transcription factor triggered by cancer-derived EVs and that ERK1/2 and JNK are upstream signaling pathways involved in EV-mediated endothelial Egr-1 activation." (PMID 25502753, 2014). "Growing evidence indicates that EGR1 activation may serve as a key switch in many pathological processes, including cardiovascular disease and cancers." (PMID 23945289, 2013). "MIG-6 (and possibly EGR1) may serve as valuable biomarkers for determining the sensitivity/suitability of a cancer type for treatment with DNMT and/or HDAC inhibitors in the clinic." (PMID 22701735, 2012). "Egr-1 has also been connected to the development of human cancers." (PMID 20087343, 2010). "Egr-1 (Early growth response 1) is a transcription factor that acts in apoptosis, angiogenesis, cell differentiation, regulates TNF production, cell proliferation and adhesion and aberrant expression of the gene is associated with several types of cancer." (PMID 19604364, 2009). "We saw significant transcriptional changes including the downregulation of key markers like EGR1 and CD24, whose reduced expression is linked to increased invasiveness and drug resistance and identified proteins such as TRIP6 and TRIM29 that enhance (cancer stem cells) CSC-like properties." (PMID 40946111, 2025). "However, EGR1 also plays pro-cancer roles in multiple gastrointestinal cancers." (PMID 39062453, 2024). "Overall, we uncover an additional layer of TFEB regulation consisting in modulating its transcription via EGR1 and propose that interfering with the EGR1-TFEB axis may represent a therapeutic strategy to counteract constitutive TFEB activation in cancer-associated conditions." (PMID 36888606, 2023). "Indeed, we highlighted three pan-cancer NFκB/TNF hallmark genes (EGR1, JUNB, and ZNF36) and identified four candidates (SRGN, CCN2, TNFRSF12A, and ZFP36L1) that are highly potentially involved in NFκB/TNF pathways in various cancers." (PMID 37475016, 2023). "Indeed, quite a lot of studies reported direct or indirect targeting of EGR1 by miR-203a, miR-377-3p, miR-125b-2-3p and miR-301b in many cancer cell lines, which slowed down the proliferation of cancer cells to a certain extent by inhibiting the expression of EGR1." (PMID 35886025, 2022). "Hence, this EGR1-MALAT1-coding genes regulatory axis may regulate pan-cancer multi-drug sensitivity/resistance through either or both cis and trans-acting mechanisms at the transcriptional and post-transcriptional level." (PMID 35534592, 2022). "Thus, the mechanisms of action of EGR1 in various cancers require additional exploration." (PMID 33842351, 2021). "Interestingly, EGF is known to promote cancer progression through EGR1 upregulation." (PMID 30845713, 2019).